SIRT5 (sirtuin 5)
Diseases named in the same sentence as SIRT5 in open-access papers (continued):
Sharing a sentence is not in itself a finding about the gene and the disease.
cardiac hypertrophy (15 papers, 2019 to 2025). "Ultimately, this process influences cardiac hypertrophy, with SIRT5 knockout causing an increased hypertrophy and a systolic impairment." (PMID 33806509, 2021). "Furthermore, mice with SIRT5 deficiency develop cardiac hypertrophy and contractile dysfunction, indicating that excessive succinylation promotes HF progression by impairing mitochondrial protein function." (PMID 41260100, 2025). "Moreover, Sirt5 knockout attenuates transverse aortic constriction (TAC)-induced cardiac hypertrophy and cardiac dysfunction in mice, which is associated with decreased ATP level, increased AMP/ATP ratio and enhanced AMPK activation." (PMID 30759120, 2019). "SIRT5 exerts a protective role in mitochondrial dysfunction and cardiac hypertrophy induced by RIP140." (PMID 39968093, 2025). "SIRT5 is essential for mitochondrial dysfunction as well as cardiac hypertrophy triggered by RIP140." (PMID 41567643, 2025). "Overexpression of SIRT5 protected cardiomyocytes from AngII-induced hypertrophy, whereas knockdown of SIRT5 resulted in cardiac hypertrophy." (PMID 39968093, 2025). "The expression of RIP140, SIRT5, and biomarkers of cardiac hypertrophy were measured by qRT-PCR and western blot." (PMID 39968093, 2025). "In contrast, knockdown of endogenous SIRT5 by RNA interference aggravated cardiac hypertrophy, providing evidence that SIRT5 plays a protective role in the pathological process of myocardial hypertrophy." (PMID 39968093, 2025). "In summary, this study unveils a novel mechanism whereby SIRT5 emerges as a crucial regulator in maintaining mitochondrial homeostasis and ultimately safeguarding against the progression of cardiac hypertrophy under the regulation of RIP140." (PMID 39968093, 2025). "A recent study compared wild type mice, SIRT5‐overexpressing mice, and SIRT5 knockout mice, all of them characterized by cardiac hypertrophy and heart failure." (PMID 39215785, 2025). "The mitochondrial SIRT3 and SIRT5 were cardiac protective factors that repress aging and pathological cardiac hypertrophy, whereas SIRT4 was reported as the only member as a pro-hypertrophic member." (PMID 33611744, 2021). "The results revealed that the knockdown of SIRT5 by si-SIRT5 could mimic the effects of RIP140 on cardiac hypertrophy by enhancing the expression of hypertrophic biomarkers and cell surface area." (PMID 39968093, 2025). "Additionally, overexpression of SIRT5 ameliorated cardiac hypertrophy by decreasing the expressions of hypertrophic markers and prevented the increase in cell size." (PMID 39968093, 2025). "Furthermore, SIRT5 significantly attenuated energy metabolic dysregulation and mitochondrial dysfunction and exerted its protective role on myocardial hypertrophy under the regulation of RIP140." (PMID 39968093, 2025). "As SIRT5 can be induced by PGC- 1α, it is tempting to speculate that SIRT5 might participate in the cardiac energy homeostasis in the progression of cardiac hypertrophy." (PMID 39968093, 2025). "However, the expression of SIRT5 in cardiovascular diseases such as myocardial hypertrophy and its regulatory mechanism related to cardiac energy metabolism are poorly defined." (PMID 39968093, 2025). "Herein, we discuss the multifunctionality of SIRT5, its impact on heart function, and its involvement as a target in geroscience for the pathogenesis of cardiovascular diseases, including heart failure, diabetic cardiomyopathy, cardiac hypertrophy, and ischemia-reperfusion injury." (PMID 41254262, 2025). "Hence, whether RIP140 could regulate SIRT5 in cardiomyocytes and their regulatory mechanism in developing cardiac hypertrophy is worthy of further investigation." (PMID 39968093, 2025). "Furthermore, SIRT2 and SIRT5 might also have protective effects on cardiac hypertrophy and fibrosis." (PMID 36581622, 2022). "Moreover, aged Sirt5 KO mice display mild cardiac hypertrophy and cardiac dysfunction." (PMID 30759120, 2019).
cardiac hypertrophy (continued). "In contrast to the protective role of SIRT5, RIP140 is widely recognized for its involvement in metabolic and mitochondrial dysfunction, thus promoting cardiac hypertrophy and subsequent transition to heart failure." (PMID 39968093, 2025). "Furthermore, RIP140 repressed SIRT5, and the inhibition of SIRT5 participated in RIP140-induced mitochondrial dysfunction and cardiac hypertrophy." (PMID 39968093, 2025). "In addition, SIRT2, SIRT5, and SIRT7 have protective effects on cardiac hypertrophy, while SIRT4 appears to have the opposite effect." (PMID 36581622, 2022). "Therefore, SIRT5 overexpression does not affect cardiac concentric hypertrophy in response to TAC." (PMID 35851833, 2022). "In the absence of SIRT5, elevated succinylation of ECHA inhibits its activity, resulting in insufficient cardiac energy supply, and triggering myocardial hypertrophy and HF." (PMID 41260100, 2025).
Sepsis (14 papers, 2018 to 2026). Sepsis is defined as life-threatening organ dysfunction caused by a dysregulated host response to infection. "In a distinct pathway, SIRT5 inhibits ferroptosis and ameliorates sepsis-induced lung injury by desuccinylating HOXA5 to upregulate FSP1 expression." (PMID 41480383, 2025). "Inhibition of the desuccinylation of pyruvate dehydrogenase mediated by SIRT5 mitigates murine burn sepsis." (PMID 39713961, 2025). "In sepsis, SIRT5 knock-out in mice aggravates renal injury and SIRT5 reduces mitochondrial damage by activating AMPK, however the exact mechanism has not been clearly demonstrated." (PMID 39000044, 2024). "Paradoxically, proinflammatory activity of Sirt5 was described during the acute and immunosuppressive phases of sepsis." (PMID 35296782, 2022). "Glutamine mitigates murine burn sepsis by essentially supporting macrophage M2 polarization, with a mechanism involving the repression of the SIRT5-mediated desuccinylation of pyruvate dehydrogenase that replenishes OXPHOS and sustains M2 macrophages." (PMID 36601059, 2022). "In contrast with SIRT1 and SIRT2, SIRT5 expression is decreased during the hypo-inflammatory phase of sepsis." (PMID 30216989, 2018). "SIRT5 deficiency decreased TLR-triggered inflammation in both the acute and the immunosuppression phases of sepsis." (PMID 30533222, 2018). "Accordingly, we hypothesized that SIRT5 regulates HOXA5 desuccinylation in sepsis‐induced lung injury." (PMID 39713961, 2025). "Indeed, Chiba and collaborators demonstrated that SIRT5−/− mice were protected from I/R while Sirt5 knock-out mice displayed aggravated sepsis-induced AKI in another study." (PMID 39000044, 2024). "We have previously shown that single deficiency in either SIRT3 or SIRT5 had no impact on host defenses in a large panel of preclinical models of sepsis." (PMID 31632409, 2019). "Finally, SIRT3−/− and SIRT5−/− mice behaved like wild-type mice in models of sepsis requiring neutrophils to fight the infectious agents." (PMID 31632409, 2019). "Emerging evidence suggest a role for SIRT5 during the hypo-inflammatory phase of sepsis." (PMID 30216989, 2018). "However, whether SIRT5–7 is related to sepsis and how they contribute to it remains to be further researched." (PMID 30533222, 2018). "Targeting this pathway, for example, by enhancing SIRT5 activity to eliminate malonyl-CoA decarboxylase or by supplying malonyl-CoA decarboxylase to consume malonyl-CoA, could be a therapeutic strategy to protect the heart (and possibly other organs) in sepsis." (PMID 41107644, 2025). "Thus, SIRT5 overexpression increased HOXA5 desuccinylation, thereby inhibiting ferroptosis in sepsis‐induced lung injury." (PMID 39713961, 2025). "Indeed, overexpressing SIRT5 in cardiomyocytes has been shown to reverse VDAC2 hypermalonylation and reduce sepsis-induced ferroptosis, further validating this approach." (PMID 41107644, 2025). "SIRT5 and SIRT1/2 have opposite expression patterns and functions in macrophages during sepsis." (PMID 39372420, 2024). "However, studies of SIRT5, SIRT6, and SIRT7 relating to the pathogenesis of sepsis are rare and need to be explored in the future." (PMID 30533222, 2018). "However, SIRT5 showed opposite expression patterns and functions compared with SIRT1 and SIRT2 in a sepsis model involving macrophages." (PMID 30533222, 2018).
Obesity (13 papers, 2017 to 2025). Accumulation of substantial excess body fat. "Similarly, a previous study demonstrates that SIRT5 deletion promotes obesity-associated osteoarthritis development." (PMID 38532359, 2024). "In mice, the genetic ablation of SIRT5 is related to enhanced susceptibility to age-related diseases, including obesity, insulin resistance, fibrosis, neurodegeneration, and cardiac dysfunction, while opposite context-dependent effects of SIRT5 have been reported with respect to tumorigenesis." (PMID 35620467, 2022). "Given the implication of BAT in glucose metabolism, SIRT5 has been suggested as a promising target for metabolic disorders such as type 2 diabetes and obesity." (PMID 39215785, 2025). "To further investigate the mechanism of action of Sirt5 deletion in mice leading to obesity and impaired thermogenesis, we performed the RNA sequencing of BAT from SIRT5-knockdown and control mice." (PMID 39408844, 2024). "Sirt5 is regulated by obesity in both BAT and iWAT, with a decreased expression found in genetically obese ob/ob mice and also in HFD-induced mice." (PMID 39408844, 2024). "Our current data support an important role for SIRT5 in mitigating diet-induced obesity and promoting adaptive thermogenesis." (PMID 39408844, 2024). "Our results show that the knockdown of Sirt5 exacerbates HFD-induced obesity and lipid metabolic disorders characterized by increased adipose tissue deposition, insulin resistance, and impaired adaptive thermogenesis." (PMID 39408844, 2024). "Acute fasting regulates Ksucc through SIRT5 to modulate lipid metabolism in adipose tissues and improve obesity." (PMID 37143582, 2023). "SIRT5 is likely downregulated during obesity, due to its role in mitochondrial respiration and β-oxidation under control of AMPK and PGC1α." (PMID 33806509, 2021). "Obesity and metabolic syndrome accelerate the occurrence of osteoarthritis during the aging process, and SIRT5‐regulated malonylation may impair chondrocyte metabolism." (PMID 37143582, 2023). "Because SIRT5 is essential in preserving BAT/WAT balance, and since BAT is involved in glucose homeostasis, SIRT5 may be a target for the therapy of certain metabolic diseases such as obesity and type 2 diabetes." (PMID 36980194, 2023). "Due to the potential role of SIRT5 as a pharmacological target in cancer, diabetes, cardiovascular diseases, obesity, neurodegenerative disorders, and inflammation, many studies have been undertaken to identify new molecules acting as SIRT5 activators or inhibitors." (PMID 35889322, 2022). "Our findings reveal that SIRT5 inhibition stimulates brown adipogenesis in vitro, supporting this approach as a strategy to stimulate BAT and counteract obesity." (PMID 34066961, 2021). "Among the target genes with the highest absolute CAP score difference are VWF (which is targeted by antihemophilic factor), SIRT5 (targeted by suramin for treating sleeping sickness), and the gastric lipase LIPF (targeted by orlistat for obesity treatment)." (PMID 29273096, 2017). "Overall, this study indicates that SIRT5 inhibition enhances brown adipogenesis and it might be a strategy to stimulate BAT and counteract obesity." (PMID 39215785, 2025). "Epididymal white adipose tissue weighs less in SIRT5 knockout mice, and lack of SIRT5 does not protect against, or promote diet-induced obesity." (PMID 33806509, 2021).
ovarian carcinoma (13 papers, 2017 to 2025). A malignant neoplasm originating from the surface ovarian epithelium. "Taken together, these results reveal a causal relationship between SIRT5 expression and cisplatin resistance in ovarian cancer cells." (PMID 31456942, 2019). "Association of SIRT5 expression with clinicopathological characteristics of ovarian cancer tissue microarrays." (PMID 31456942, 2019). "In addition, high levels of SIRT5 are reportedly associated with improved outcomes for ovarian cancer patients, which was in accordance with our results." (PMID 33796460, 2021). "In ovarian cancer, miR-27b-5p suppresses the invasive capacity of ovarian cancer stem cells (OCSCs) by directly targeting SIRT5." (PMID 40710326, 2025). "SIRT5 overexpression facilitates ovarian cancer cell growth and cisplatin-resistance in an in vitro A2780 cell model, because SIRT5 suppresses cisplatin-induced DNA damage by increasing NRF2 and Haem Oxygenase 1 (HO-1) expression." (PMID 35453348, 2022). "As the multiple protein modification functions of SIRT5, the protective role on ovarian cancer remains for further investigations." (PMID 35252174, 2022). "Some researchers also found that SIRT5 was upregulated in cisplatin-resistant ovarian cancer cells compared with cisplatin-sensitive cells." (PMID 35136826, 2022). "In this study, among the Sirtuin family, SIRT5 was highly expressed in ovarian cancer compared to its expression in normal tissues, based on the GEPIA database and this result was verified by immunohistochemistry." (PMID 31456942, 2019). "In summary, SIRT5 expression is increased in ovarian cancer tissues and high SIRT5 levels predict poor chemotherapy response." (PMID 31456942, 2019). "In conclusion, our study implies that SIRT5 expression is increased in ovarian cancer tissues and its high level predicts a poor chemotherapy response." (PMID 31456942, 2019). "BRCA1, which is a key gene in the DNA damage repair pathway, was identified as having a positive correlation with SIRT5 expression in ovarian cancer, based on the GEPIA database." (PMID 31456942, 2019). "SIRT5 was found to promote resistance to cisplatin in ovarian cancer cells, raising the question of how SIRT5 participates in the induction of chemoresistance." (PMID 31456942, 2019). "Here, we demonstrate that SIRT5 is increased in ovarian cancer tissues compared to its expression in normal tissues and this predicts a poor response to chemotherapy." (PMID 31456942, 2019). "SIRT5 was more highly expressed in ovarian cancer tissues than in normal tissues and was mainly localized to the cytoplasm." (PMID 31456942, 2019). "SIRT5 is overexpressed in ovarian cancer tissues and promotes cisplatin resistance in ovarian cancer cells by inhibiting cisplatin-induced ROS-dependent DNA damage by regulating the nuclear factor erythroid 2-related factor 2 (Nrf2)/heme oxygenase 1 (HO-1) pathway." (PMID 36505774, 2022). "In addition, SIRT5 was found to promote cisplatin resistance (HO-1) pathway in ovarian cancer by modulating Nrf2/heme oxygenase 1 axis." (PMID 35136826, 2022). "Considering the diverse roles of SIRT5 in cancer biology, we speculated that SIRT5 is a therapeutic target for ovarian cancer." (PMID 31456942, 2019). "Furthermore, we reveal a potential role for SIRT5 in ovarian cancer cell growth and chemoresistance." (PMID 31456942, 2019). "Moreover, a significant, positive correlation was identified between Nrf2 and SIRT5 mRNA expression in ovarian cancer based on the GEPIA database (P = 1.5e-10, R = 0.3)." (PMID 31456942, 2019). "Mechanistically, we show that SIRT5 contributes to cisplatin resistance in ovarian cancer by suppressing cisplatin-induced DNA damage in a reactive oxygen species (ROS)-dependent manner via regulation of the nuclear factor erythroid 2-related factor 2 (Nrf2)/heme oxygenase 1 (HO-1) pathway." (PMID 31456942, 2019).
ovarian carcinoma (continued). "Therefore, in this context, we investigated the expression pattern of SIRT5 in both human ovarian cancer tissues and ovarian cancer cells." (PMID 31456942, 2019). "In addition, high levels of SIRT5 predicted shorter PFS and were positively associated with clinicopathologic characteristics of ovarian cancer, such as advanced FIGO stage and lymph node metastasis, but were negatively correlated with differentiation." (PMID 31456942, 2019). "We also reveal a potential function for SIRT5 in ovarian cancer proliferation and chemoresistance." (PMID 31456942, 2019). "Therefore, SIRT5 was shown to promote cisplatin resistance in ovarian cancer cells by inhibiting DNA damage." (PMID 31456942, 2019). "As SIRT5 was hypothesized to play a role in ovarian cancer development and chemoresistance, its effect on the biological behaviors of the three cell lines was investigated." (PMID 31456942, 2019). "Therefore, SIRT5 might serve as a prognostic factor for ovarian cancer and SIRT5 inhibitors combined with chemotherapy could represent a novel therapeutic strategy for ovarian cancer patients." (PMID 31456942, 2019). "Consequently, we speculated that SIRT5 is involved in the progression and chemoresistance of ovarian cancer." (PMID 31456942, 2019). "SIRT5 levels were also found to be higher in cisplatin-resistant SKOV-3 and CAOV-3 ovarian cancer cells than in cisplatin-sensitive A2780 cells." (PMID 31456942, 2019). "Interestingly, SIRT5, a mitochondrial NAD-dependent deacetylase, is increased in ovarian cancer tissues, predicting a poor response to chemotherapy." (PMID 35453348, 2022). "Moreover, SIRT5 levels are higher in cisplatin-resistant SKOV-3 and CAOV-3 ovarian cancer cells than in cisplatin-sensitive A2780 cells." (PMID 35453348, 2022). "In contrast to SIRT3, the roles of the other two mtSIRTs, SIRT4 and SIRT5, are not yet explored in ovarian cancer, though their dual puzzling functions as tumor suppressors and tumor promoters have been reported in other cancers." (PMID 31113446, 2019).
heart failure (12 papers, 2021 to 2025). Inability of the heart to pump blood at an adequate rate to meet tissue metabolic requirements. "Consistent with the previous findings, the SIRT5 KO TAC model accelerated cardiac failure with high mortality and showed metabolic dysfunction including defective OxPhos, decreased fatty acid oxidation, and a low NAD+/NADH ratio but increased glycolysis." (PMID 38213532, 2023). "SIRT5 has been reported to exhibit a protective role in the pathological process of AMI, as global knockout of SIRT5 increased the infarct size in a model of cardiac ischemia-reperfusion injury and developed heart failure." (PMID 34368135, 2021). "As previously reported, quercetin stimulated SIRT5 expression, inhibited oxidative stress damage and inflammation, maintained cardiomyocyte activity, and reduced myocardial fibrosis damage in mice with heart failure." (PMID 39979670, 2025). "Studies have shown that quercetin can promote the desuccinylation of IDH2 through SIRT5, maintain mitochondrial homeostasis, protect mouse cardiomyocytes under inflammatory conditions, and improve myocardial fibrosis, to reduce the incidence of heart failure." (PMID 39979670, 2025). "Sirt5 KO mice are more susceptible to injury and dysfunction after cardiac stress, but the mechanism cannot be determined and it can only speculate that SIRT5 overexpression may prevent hypertrophy and heart failure by regulating levels of succinic acid and other metabolites." (PMID 39979670, 2025). "Previous research on the SIRT family has demonstrated that in a model of heart failure induced by transverse aortic constriction (TAC), the expression levels of SIRT5 are markedly diminished." (PMID 40093797, 2025). "Compared to SIRT1, SIRT3, and SIRT6, studies on SIRT2,541 SIRT4, SIRT5,542 and SIRT7 in heart failure are limited." (PMID 36581622, 2022). "Studies on SIRT2, SIRT4, SIRT5, and SIRT7 might reveal promising research directions for the treatment of heart failure." (PMID 36581622, 2022).